IL2 (interleukin 2)
Diseases named in the same sentence as IL2 in open-access papers (continued):
Sharing a sentence is not in itself a finding about the gene and the disease.
infection (continued). "Three days post-infection, cells were transferred to media containing 10 U/ml IL2 and transduced with lentiviral particles expressing shRNAs." (PMID 29554134, 2018). "OT-II cells expressing both IFNγ and IL-2 significantly increased in LdWT (p = 0.0064) and LdCen−/− (p = 0.0489) infections upon blocking with α-CD200 antibodies." (PMID 29915577, 2018). "Levels of TNF-α, IL-10 and IL-2 differed between groups on SD 1 already, i.e. before infection, but these discrepancies are compensated for by the paired analysis (normalization to SD 1) applied here." (PMID 29973271, 2018). "Interleukin-2 (IL-2) is an immunomodulatory cytokine that is critical during infections for activating and directing lymphocyte function." (PMID 29709039, 2018). "In contrast, the infection alone showed an inadequate drop in IFNγ, IL-2, and IL-10 levels over the course of infection." (PMID 29740435, 2018). "The transcription levels of rat IL-2 in vitro were investigated by RT-PCR analysis after C6 cells were infected with 5 multiplicity of infection (MOI) of VVs, which was consistent with ELISA assay results." (PMID 29701680, 2018). "Experimentally infected cattle have increased IL-2 and IFN-γ production in the first 2 to 3 weeks postinfection, while our study suggests that the early stages of natural infection are associated with increased IL-4 production and IL-5 transcription." (PMID 28993458, 2018). "Although serum IL-2 levels were generally low, they were elevated in the infected groups with respect to levels in healthy mice, dropping back over the course of infection." (PMID 29740435, 2018). "Results from these analyses indicated that sagA complemented GAS induces a 2-fold or greater increase in I-309, IL-1α, IL-1β, IL-2, IL-15, MCP-3, MIG, and MIP-1δ compared to the SLS-deficient mutant infection." (PMID 30018884, 2018). "Cytokine IL-2 in mice lung decreased after PR8 infection, oseltamivir and SJS displayed the same tendency that they increased the level of IL-2." (PMID 29739459, 2018). "The most critical factors highlighted during the analysis of the Treatment response model include IL-10, IL-21, IL-12, IL-2 which determine the treatment outcome in terms of clearance of infection by modulating pro-inflammatory response." (PMID 29891859, 2018). "Beside IL-15 and IL-18, NK cell activation depends on IL-2 that is predominantly produced by activated CD4+ T cells during many infections." (PMID 30210499, 2018). "Within the cytokines analysed in this study; Flt-3L, GM-CSF and IL-2 were all significantly elevated in cats with a diagnosis of infection with an MTBC organism compared to all other groups." (PMID 30470763, 2018). "At the initial infection, macrophages infected by T. gondii tachyzoites produced interleukin (IL-2), tumor necrotic factor-α, IL-β, and IL-15." (PMID 29062190, 2017). "To examine the association of circulating common γ-chain cytokines with TB disease or infection, we examined the systemic levels of IL-2, IL-7, IL-15, and IL-21 in individuals with PTB, latent TB (LTB) or no TB infection (NTB)." (PMID 28448542, 2017). "As recently shown in mice, the robust immune reaction expressed by the high IFN-γ levels in the acute phase of the infection severely reduces the activity of Tregs in a IL-2 dependent and IL-10 independent manner." (PMID 28642841, 2017). "We demonstrated that GRAIL expression during infection was modulated by the mammalian target of the rapamycin (mTOR) pathway, since addition of IL-2 or CTLA-4 blockade in splenocytes from mice 21 days post infection led to a reduction in GRAIL expression." (PMID 28114324, 2017). "Similar results were obtained following delivery of rIL-2 protein, IL-2 DNA or IL-2 synthetic peptides prior to infection with different strains of HSV-1." (PMID 28542613, 2017). "In serum, IFN-γ increased slightly and IL-2 was downregulated during early days of infection, while Th2 cytokines IL-4 and IL-10 increased during the whole intestinal phase." (PMID 29163382, 2017).
infection (continued). "Animal and human studies of intracellular pathogens have extensively evaluated polyfunctional CD4+ T cells producing multiple pro-inflammatory cytokines (IFN-γ, TNF-α, and IL-2) as a possible correlate of protection from infection and disease." (PMID 29051764, 2017). "Counter-regulatory mechanisms are instructed early in the response to infection to temper collateral tissue damage, regulatory mechanisms that are also induced during IL-2 therapy." (PMID 28815218, 2017). "In the canarypox prime/protein boost RV144 trial, the elicitation of five-function T cells expressing CD40L, IL-2, IL-4, IFN-γ, and TNF-α or three-function T cells expressing CD40L, IL-2, and IL-4 correlated with a reduced risk of infection." (PMID 29021394, 2017). "Here we link the increase in Treg frequency and Treg CD25, CTLA-4 and FOXP3 expression to the infection-induced release of IL-2, detectable in the serum." (PMID 28815218, 2017). "IL-2 presented the highest mRNA level change (137-fold) at 5 days post infection (dpi) in the magnum." (PMID 27846843, 2016). "In order to assess the impact of IL-2/anti-IL-2 complex-mediated expansion of non-CD4 immune cell populations in the murine ear dermis infection model, we combined the anti-CD4-mediated reactivation of Mtb with the expansion of non-CD4 immune cell populations." (PMID 27391012, 2016). "Later in infection, or during re-infection, after the differentiation of antigen-specific T helper cells and production of antibodies, IL-18 synergizes with IL-2 and with antibody-antigen complexes to enhance ADCC and IFN-γ production." (PMID 27047490, 2016). "A previous report described the generation of iPSCs from PBTCs by stimulating them twice with anti-CD3 monoclonal antibody (mAb) and IL-2 5 days apart followed by infection with SeV vectors." (PMID 27057178, 2016). "We conclude that infections by S. pyogenes in young children lead to an increased expression of IL-2 mRNA." (PMID 27493590, 2016). "Once infection is cleared, the infection-induced expression of 4-1BBL on the surface of APCs declines, which in turn translates into the cessation of IL-2 and IFN-γ expression and restoration of immune suppression." (PMID 27049955, 2016). "CD4+ T cells were cultured in IL-2+ Ritonavir for single round infection, or additionally stimulated with PHA which resulted in a strong induction of activation measured by CD25 and CD69." (PMID 27383627, 2016). "For instance, IFN-γ and IL-2 can activate inflammation, but these cytokines also have benefits related to pathogen clearance that can be relevant in efforts to avoid infection in the later stages of critical aggression." (PMID 28070142, 2016). "The data showed that, along with the infection, the IL-2 mRNA level of CD4+ T cells was gradually reduced compared to the uninfected cells." (PMID 27145859, 2016). "Studies on bile and serum of patients indicated that infection with C. sinensis correlated with Th2 type responses, emphasizing the decrease in concentration in IL-2 and an increase in IL-4." (PMID 27348302, 2016). "It has been shown that NK cells become ‘primed' upon exposure to cytokines such as IL-2 or IL-15 and, in turn, have enhanced reactivity against target cells, a situation that likely occurs during the course of infection and transformation." (PMID 27221592, 2016). "METH actually increased the linear trend of both decreased IL-2 and CD107a expression during the course of infection." (PMID 27760221, 2016). "Our findings indicate that early after infection, robust IFN-γ/TNF-α responses by Tcm are associated with greater mycobacterial burden, while IFN-γ/TNF-α/IL-2 responses by Tcm cells are indicative of a protective response." (PMID 27799930, 2016). "Intriguingly, the proportion of Foxp3+ cells expressing CD25 increased as a result of infection, mainly after 21 days of infection, coinciding with the minimal IL-2 contents." (PMID 26745276, 2016).
infection (continued). "A surprising finding in this study was the decreased level of systemic IL-1β and IL-2 in the SmPCR+ cohort compared to Sm uninf and those with patent infection." (PMID 27152725, 2016). "The results showed that the concentration of IL-2 and IL-17 was statistically increased in the groups treated with JS after infection, whereas the level of IL-4 was significantly decreased." (PMID 27558409, 2016). "To specifically address the phenotype and multifunctionality of responding T cells, we performed intracellular cytokine staining (ICS) for the expression of IFN-γ, TNF-α, and IL-2 following in vitro restimulation (infection strain, MOI = 0.1)." (PMID 27512056, 2016). "IL-2/IFN-γ/TNF-α co-expression remained quite stable during the entire course of infection (from day 14 to day 56)." (PMID 27760221, 2016). "As expected, T helper-1 cytokines including interferon-γ and interleukin-2 were significantly elevated by infection with the nahG transfectant." (PMID 26466097, 2015). "In the present study, the effects of the chicken IL-2 gene expression during in vivo infection of SPF chickens by a virulent NDV were investigated." (PMID 26253150, 2015). "The results showed that the production of IFN-γ, IL-2 and IL-12 (Th1-related cytokines) were elevated at 4 weeks post-infection and peaked at 7 weeks post-infection." (PMID 25590646, 2015). "GITR triggering also boosted the helper function of virus-specific CD4 T cells already early in the infection, as was evidenced by increased IL-2 and IFNγ production, and more expression of CD40L and T-bet." (PMID 25738498, 2015). "As the indicator for activated Th1 lymphocytes, the pro-inflammatory cytokines including IFN-γ and IL-2 are also involved in the protection against the infection." (PMID 25886737, 2015). "IFN-γ+TNF-α+IL-2+ multifunctional CD4+ T cells were present in the blood of all infected animals at one or two weeks after primary infection and their frequency increased in four out of six animals after homologous secondary infection." (PMID 25971313, 2015). "At the site of infection (eyelid), expression of IL-2 was demonstrated in areas of rZJ-IL2 replication, confirming IL-2 production in vivo." (PMID 26253150, 2015). "Animals treated with 200 mg/kg bw of ALE and ASE produced significant levels of INF-γ, TNF-α, and IL-2 with respect to infection control (P < 0.05)." (PMID 25884649, 2015). "EDLF at the early stages p.i. drastically inhibited the infection-induced IL-2 generation, while upregulated IL-10, which inhibits Th1 inflammatory response." (PMID 26191954, 2015). "Although much lower levels of CD25 were detected on splenic NK cells 24 h after infection with the lethal strain of P. yoelii, these also showed increased sensitivity to exogenous IL‐2 with substantially augmented IFN‐γ responses." (PMID 26420375, 2015). "The expression levels of il2, il4, and ifngamma were below the detection limit in all tissues in this round of infection experiments." (PMID 26146835, 2015). "The patient that still showed signs of infection after more than 2 years of antibiotic treatment (patient 3), had markedly high IL-2 secretion and a low IFN-γ/IL-2 ratio from the start, which fluctuated in the follow-up but did not decrease." (PMID 25729380, 2015). "Historically, low levels of T cell cytokines (IL-2, IL-3, IL-4, IL-5, IL-9, IL-13) have been observed in fatal human cases of infection with EBOV and in infection of NHPs with MARV." (PMID 26512687, 2015). "Of the adaptive cytokines, only IL-2 showed a sustained and substantial increase in mRNA expression levels following infection, and only in the thymus and bone marrow." (PMID 26244502, 2015). "In this study, we constructed a transgenic Eimeria mitis line (EmiChIL-2) expressing chicken IL-2 (ChIL-2) to investigate the adjuvant effect of ChIL-2 to enhance the immunogenicity of E. mitis against its infection." (PMID 26082759, 2015).
infection (continued). "The patterns of IFN-γ, IL-2, and serum neutralizing antibodies were similar, and there were significant difference between the youngest ducks and the older ducks at early infection stage (P < 0.05)." (PMID 26106382, 2015). "We observed a considerably enhanced CD25+ pSTAT5+ population from TGF-βRII KO early effector cells relative to the WT cells, suggestive of heightened IL-2 signaling in the TGF-βRII KO CD4 T cells in vivo during infection." (PMID 25569154, 2015). "As the infection developed, the ratio of Treg increased, the level of IL-6 decreased to a normal level, and IL-2 sharply increased." (PMID 26599407, 2015). "TBE vaccination also induces robust Th1 responses, which, after booster vaccination and with respect to IL-2, were significantly higher than that after natural infection." (PMID 26465323, 2015). "After infection, cells were kept in an activated state by returning them to culture in the presence of activating beads and IL-2." (PMID 26067822, 2015). "As a positive control, resting CD4+ T cells were stimulated with αCD3/αCD28 activating beads in the presence of IL-2 for 72 h prior to infection, which led to significant expression of both CD69 and CD25 activation markers." (PMID 26067822, 2015). "The first peak occurred early during infection, over days 3–7 post-challenge (CSG IL1 and IL6), while the second wave occurred during acute symptomatic infection over days 10–14 post-challenge (CSGs IL2, IL3, IL7–IL10)." (PMID 25014551, 2014). "All patients should be carefully screened for infection prior to IL-2 treatment and any active infection should be fully treated and the patient should be off antibiotics prior to starting a cycle of HD IL-2." (PMID 31546315, 2014). "This study also shows that the high level expression of three Th-1 cytokines namely IFN-γ, TNF-α and IL-2 by antigen-stimulated spleen cells at the time of infection correlates with the level of protection against L. major infection in mice." (PMID 25500571, 2014). "By 24 weeks post infection, the TH1 cytokines, IFN-γ and IL-2, showed a decrease in overall levels compared with 12 weeks post infection, but they were still significantly upregulated from controls (p = 0.002, p = 0.0004)." (PMID 24551602, 2014). "Multiparametric flow cytometer analysis of stimulated spleen cells shows that mice immunized with pcDNA-mGMCSF-LdPx1 kept high IFN-γ, TNF-α, and IL-2 response eight weeks post-infection." (PMID 25500571, 2014). "The majority of the present study was performed in IL2/PHA-activated T cells in order to allow for infection with HIV in vitro." (PMID 24404168, 2014). "This study provided some basic data on the optimal time to observe different immune parameters, for example, IL-2+, IL-4+ CSCs stimulated about 12 days post infection, TNF-α, IFN-γ, IL-10 cytokines only transiently increased in the early infection." (PMID 24725777, 2014). "Fevers and chills which occur outside the 2-6 hour window after a dose of IL-2 must be considered as potentially due to infection and evaluated accordingly." (PMID 31546315, 2014). "IL-2 is also required for fighting against infection and germs as research has shown that IL2_/_ mice themselves spontaneously develop multi-organ inflammation." (PMID 24887408, 2014). "Later in infection, FP-inoculated mice initiated a strong T cell response, with significantly higher production of IFNγ, TNFα and IL-2 than IN-inoculated mice." (PMID 24922480, 2014). "On the other hand, the high dose group (109 CFU/mouse), showed significant release of IFN-γ (p = 0.03), IL-2 (p = 0.02), and IL-10 (p = 0.01) in harvested spleenocytes stimulated with Johnin compared to media only controls by 12 weeks post infection." (PMID 24551602, 2014). "Contrast to IFN-γ+ CSCs increasing from the early infection, IL-2+ and IL-4+ CSCs only increased 12 days post infection, which implied the strongly stimulated adapted immune response." (PMID 24725777, 2014).
infection (continued). "When stimulated with the combination of aminobisphosphonates and IL-2 activate the Vγ9Vδ2 T cells further and they can also act as the APCs to treat particular infections and tumors." (PMID 25426120, 2014). "Particularly important is that H1/IC31 induces multifunctional T cells expressing TNF-α and IL-2, markers of central memory T cells, which are required for long-term protection against both reactivation and infection." (PMID 25490675, 2014). "Most importantly, administration of IL-2:anti-IL-2 complex also evoked a dramatic switch in infection status." (PMID 24185641, 2014). "In particular, a dramatic shift towards Th1 phenotype and most probably an effective CMI response was maintained by high IL-12 and IL-2 mRNA levels even at 3 months post infection in cocktail vaccinates." (PMID 25144181, 2014). "Similar comparisons between patients infected with different Leishmania indicated that infection with L. guyanensis led to higher seric levels of both IL-2 (P = 0.0002) and IFN-γ (P = 0.0412) than those from patients infected with L. amazonensis." (PMID 25295285, 2014). "Th-1 cytokines such as IFN-γ, TNF-α, and IL-2 favor resistance to infection while IL-4, IL-10 and IL-13 mediate disease progression and parasite persistence." (PMID 25500571, 2014). "IL-2+ and IL-4+ secreting cells showed significant increase 12 days post infection, while IFN-γ+, IgG+ and IgA+ secreting cells increased 6 days post infection." (PMID 24725777, 2014). "A granulocyte migration defect observed in patients receiving HD IL-2 was postulated to have permitted local infections to become systemic." (PMID 31546315, 2014). "We found that, compared to the IL-2 only treated group, CHDMAPP and IL-2 co-treatment significantly increased the proportion of circulating T cells that were γ9+ pre-infection (P<0.01) and post infection (P<0.001)." (PMID 24098670, 2013). "We have got lower (0.83085) c-value for IL-2, which has become higher (0.84865) at the time of infection, and has again been lower (0.83404) when we optimized the integrated pathway system for two conflicting objective functions." (PMID 24324645, 2013). "qRT-PCR results revealed significant (p<0.05) induction of IL-1β, IL-2, and IFNγ transcription, with the greatest induction observed upon infection with the chicken-origin isolate." (PMID 23521892, 2013). "After infection, a higher proportion of NK cells degranulated in the presence of only IL-2 than before infection." (PMID 23326405, 2013). "Both Tregs and TH1 cells activated by infection induce phosphorylation of STAT5 in response to IL-2." (PMID 23754944, 2013). "Triple-positive polyfunctional CD4+ T cells were evaluated in the spleen, and although Mtb induced increases in spleen CD4+IFN-γ+ and CD4+IL2+ cells, the infection significantly reduced the frequencies of triple-positive CD4+TNF-α+IFN-γ+ cells." (PMID 24250805, 2013). "By administering the antiretroviral drugs RGV and AZT post-infection, we established that most of the virus produced in our assays came from the ability of Prostratin or IL-2 to promote de novo infection after an initial burst of virus production." (PMID 23201205, 2013). "We sought to confirm the role of DCIR in HIV-1 attachment and transmission via CD4TL by treating the cells with H2O2 before pre-incubation with the selected DCIR inhibitors (HIV-1 trans infection of PHA-L/IL2-activated CD4TL via apoptotic CD4TL)." (PMID 23874461, 2013). "Recently, it was shown that a strong polyfunctional CD8+ T cell response capable of coproducing TNF-α and IL-2 in additional to IFN-γ was required to control the progressive infection of viruses like HIV and HCV." (PMID 23476150, 2013). "When healthy controls and patients with infection were compared, IL2 and IL23 gene expression was lower in patients with infection, and gene expression of IL10 and IL27 were greater in patients with infection." (PMID 23935244, 2013).